HNRNPA2B1 (heterogeneous nuclear ribonucleoprotein A2/B1)
Diseases named in the same sentence as HNRNPA2B1 in open-access papers (continued):
Sharing a sentence is not in itself a finding about the gene and the disease.
proteinopathy (6 papers, 2020 to 2024). "Mutation of LCD in m6A regulators, such as hnRNPA2B1, results in ectopic production of SGs, which leads to multisystem proteinopathy." (PMID 39239525, 2024). "Mutations in the heterogeneous nuclear ribonucleoprotein A2/B1 (hnRNPA2B1) and hnRNPA1 genes were identified as a cause of multisystem proteinopathy in which PDB was a component part by a genome sequencing approach in families [35••]." (PMID 33988819, 2021).
atherosclerosis (5 papers, 2022 to 2025). A disease characterized by the build-up of fatty material and calcium deposition in the arterial wall resulting in partial or complete occlusion of the arterial lumen. "First, we analyzed the expression of hnRNPA2B1 in human coronary artery segments with different stages of atherosclerosis by immunohistochemical staining." (PMID 37990246, 2023). "The results highlighted circZBTB46 as a promising therapeutic target that plays an important role in atherosclerosis progression by interacting with hnRNPA2B1 and regulating its ubiquitination and degradation." (PMID 37990246, 2023). "We may, hence, hypothesize that hnRNPC and hnRNPA2B1 downregulation could reduce the deleterious effects that m6A increase has in atherosclerosis RNA metabolism and alternative maturation." (PMID 37570694, 2023). "In addition, the downregulation of heterogeneous nuclear ribonucleoprotein A2/B1 (HNRNPA2B1) protects against atherosclerosis by suppressing VSMC proliferation." (PMID 36899956, 2023).
oculopharyngeal muscular dystrophy (5 papers, 2017 to 2024). Oculopharyngeal muscular dystrophy (OPMD) is an adult-onset progressive myopathy characterized by progressive eyelid ptosis, dysphagia, dysarthria and proximal limb weakness. "In pediatric patients, however, only HNRNPA2B1 is known to cause a childhood‐onset myopathy, resulting in a phenotype reminiscent of oculopharyngeal muscular dystrophy but with an exceedingly early onset." (PMID 36651622, 2023). "Taking into account the clinical similarities between our patient and HNRNPA2B1‐associated oculopharyngeal muscular dystrophy, we colabeled control and patient muscles using α‐ANXA11 and α‐hnRNPA2B1." (PMID 36651622, 2023). "Because of the report of variants in HNRNPA2B1 in patients with oculopharyngeal muscular dystrophy, we reanalyzed this gene in the patient." (PMID 36651622, 2023). "Here the authors report an oculopharyngeal muscular dystrophy caused by heterozygous frameshift mutations in HNRNPA2B1 that alter its nucleocytoplasmic transport dynamics and result in cytoplasmic accumulation of hnRNPA2 protein." (PMID 35484142, 2022).
fragile X-associated tremor/ataxia syndrome (4 papers, 2016 to 2024). Fragile X-associated tremor/ataxia syndrome (FXTAS) is a rare neurodegenerative disorder characterized by adult-onset progressive intention tremor and gait ataxia. "hnRNPA2B1 could be involved in Fragile X-associated tremor/ataxia syndrome (FXTAS), a late onset disorder inducing a form of mental retardation." (PMID 32292882, 2020). "The interactors hnRNPA1, hnRNPA2B1, Matr3, FMRP and Prkra have previously been associated with neurodegenerative diseases (ALS, multisystem proteinopathy, fragile X-associated tremor/ataxia syndrome (FXTAS), fragile-X syndrome (FXS) and dystonia parkisonism)." (PMID 27164932, 2016).
head and neck cancer (4 papers, 2022 to 2024). A primary or metastatic malignant neoplasm affecting the head and neck. "HNRNPA2B1 also was identified as an oncogene in head and neck cancer, which promotes epithelial to mesenchymal transition through the AKT/PKB signaling pathway." (PMID 36401285, 2022). "HNRNPA2B1 was another important factor, which was identified as an oncogene in head and neck cancer and could promote Akt/PKB signaling by upregulating the RONΔ165 isoform, thereby promoting epithelial-mesenchymal transition of head and neck cancer cells." (PMID 36271283, 2022).
lung adenocarcinoma (4 papers, 2017 to 2022). A carcinoma that arises from the lung and is characterized by the presence of malignant glandular epithelial cells. "We also found that HNRNPA2B1 with different methylation levels causes a varied prognosis in lung adenocarcinoma (LUAD)." (PMID 35529270, 2022). "A recent study showed that phenanthrene-based tylophorine-1 (PBT-1) binds to hnRNPA2B1 and exerts antitumor activity in part by reducing AKT-mediated lung adenocarcinoma metastasis and tumorigenesis." (PMID 28993733, 2017).
oral squamous cell carcinoma (4 papers, 2021 to 2023). "In a previous study, patients with oral squamous cell carcinoma who had higher HNRNPA2B1 expression had a poor prognosis." (PMID 35529270, 2022). "Studies found that HNRNPA2B1 was the most critically prognostic locus of m6A regulatory genes in oral squamous cell carcinoma(OSCC), silence of HNRNPA2B1 could inhibit the proliferation, migration, and invasion of OSCC by inducing epithelial-to-mesenchymal transition(EMT)." (PMID 34899855, 2021).
Paget disease (4 papers, 2016 to 2023). A malignant neoplasm composed of large cells with large nuclei, prominent nucleoli, and abundant pale cytoplasm (Paget cells). "On case note review, neither patient with the hnRNPA2B1 variant or the SQSTM1 variant had evidence of multisystem disease typical of the genes (inclusion body myopathy or Paget’s disease)." (PMID 36515702, 2023).
pulmonary arterial hypertension (4 papers, 2022 to 2025). Pulmonary arterial hypertension (PAH) is a group of diseases characterized by mean pulmonary artery pressure >20 mmHg and elevated pulmonary arterial resistance leading to right heart failure. "Emerging preclinical evidence suggests that HNRNPA2B1 silencing attenuates monocrotaline (MCT)-induced pulmonary hypertension (PH) in rat models." (PMID 40703632, 2025). "Animal experiments demonstrate that HNRNPA2B1 interference reverses pulmonary hypertension in MCT-induced rat models." (PMID 40703632, 2025). "The results of the bioinformatics analysis suggest that HNRNPA2B1 was significantly elevated in pulmonary hypertension and plays an important functional role in SMCs." (PMID 36171892, 2022). "In conclusion, HNRNPA2B1 may regulate the initiation and progression of pulmonary hypertension through inflammatory signaling pathways." (PMID 40703632, 2025).
renal carcinoma (4 papers, 2020 to 2024). A carcinoma arising from the epithelium of the renal parenchyma or the renal pelvis. "It has also been demonstrated that HNRNPA2B1 is a reader of m6A, which is downregulated in renal cancer, and that this downregulation is associated with a poorer prognosis." (PMID 39268079, 2024). "Our previous study also uncovered that VHLα negatively regulated hnRNPA2B1 and eventually modulated pyruvate kinase transcript splicing and reprogramed cellular glucose metabolism in renal cancer cells." (PMID 32826868, 2020). "Our previous data uncovered the self-limiting regulation of hnRNPA2B1 via feedback loop with VHLα in renal cancer cell." (PMID 32826868, 2020). "We would like to emphasize the distinct finding of our study in respect of c-myc-recognizing site in hnRNPA2B1 promoter in renal cancer." (PMID 32826868, 2020). "Our previous study demonstrated VHLα other than both VHL-19 and VHL-24 was capable of degrading hnRNPA2B1 in renal cancer cells." (PMID 32826868, 2020). "We further identified aberrant overexpression of c-myc as upstream oncogenic signaling to positively regulate hnRNPA2B1 transcription in renal cancer." (PMID 32826868, 2020). "In agreement with previous report, here we described c-myc-mediated regulation of hnRNPA2B1 transcription in renal cancer cells." (PMID 32826868, 2020). "Therefore, hnRNPA2B1 highly likely exert oncogenic functions in the context of c-myc activation and VHLα disruption in renal cancer." (PMID 32826868, 2020). "Our study also uncovered the pro-tumoral activities of hnRNPA2B1 in renal cancer cells." (PMID 32826868, 2020). "Therefore, our results clearly demonstrated hnRNPA2B1 transcription was subjected to c-myc in renal cancer cells." (PMID 32826868, 2020). "Our previous study identified a novel VHLα isoform which negatively modulated hnRNPA2B1 expression and therefore influenced pyruvate kinase transcript splicing in renal cancer, while the regulation and initiation of alternative translation are largely unknown." (PMID 32826868, 2020).
rheumatoid arthritis (4 papers, 2006 to 2025). A chronic, systemic autoimmune disorder characterized by inflammation in the synovial membranes and articular surfaces. "Referring to immunity, hnRNPA2B1 can not only increase the antiviral innate immune response to DNA viruses, but also may be a potential marker for the early stage of the disease in the pathogenesis of rheumatoid arthritis, because immunity is essential for the occurrence and development of tumors." (PMID 34630502, 2021).
sarcoma (4 papers, 2022 to 2024). A usually aggressive malignant neoplasm of the soft tissue or bone. "Interestingly, some known regulatory relationships were also identified in sarcoma, such as HNRNPA2B1-miR-106b, HNRNPA2B1-miR-17 and HNRNPA2B1-miR-93." (PMID 35847857, 2022).
type 2 diabetes (4 papers, 2022 to 2026). "Among the 15 m6A-RMRs upregulated in four different tissues in type 2 diabetes, one regulator HNRNPA2B1 (reader) was shared by liver, subcutaneous adipose, and visceral adipose, and one regulator G3BP1 was shared by liver and visceral adipose." (PMID 35211628, 2022).
adrenocortical carcinoma (3 papers, 2022 to 2023). "It is noteworthy that HNRNPA2B1 levels are connected with cancer-associated fibroblasts in cancers, such as adrenocortical carcinoma, LUAD, and stomach adenocarcinoma." (PMID 35529270, 2022). "Recent research in adrenocortical carcinoma (ACC) has shown that HNRNPA2B1 affects tumor development by regulating infiltration of M0 macrophages into the TME." (PMID 37546413, 2023). "The HEPIA2 dataset revealed an association of HNRNPA2B1 levels with the clinicopathological stages of adrenocortical carcinoma (ACC), but not with those of BLCA, BRCA, LUAD, LUSC, and OC." (PMID 35529270, 2022).
breast tumors (3 papers, 2010 to 2024). "Inhibition of hnRNPA2B1‐mediated m6A recognition can suppress breast tumor growth in vivo and increase the chemotherapeutic effectiveness of BC." (PMID 38626369, 2024). "Given the significant role of hnRNPA2B1 in exporting CSC‐related mRNAs in breast tumor cells, we hypothesized that targeting hnRNPA2B1 could abrogate chemoresistance in breast tumor." (PMID 38626369, 2024).
clear cell renal cell carcinoma (3 papers, 2020 to 2024). "In conclusion, we built up a three-m6A methylation regulators-based RS of METTL3, METTL14 and HNRNPA2B1 that may become potential biomarker for prognosis prediction of clear cell renal cell carcinoma patients, our results call for further experimental studies for validations." (PMID 32219036, 2020).
COVID-19 (3 papers, 2022 to 2023). A disease caused by infection with severe acute respiratory syndrome coronavirus 2. "We observed that RBM15B, HNRNPA2B1, and VIRMA may be protective factors in the development of COVID-19, and the opposite performance was found in ELAVL1, RBM15, FMR1, IGFBP3, and METTL3." (PMID 35655464, 2022).
diabetes (3 papers, 2022 to 2025). "qRT-PCR analysis showed that Fus, Hnrnpa2b1, Canx, Calr, and Polr2a were the significant difference in mRMVECs and Fus, Hnrnpa2b1, Canx, and Calr were the significant difference in the diabetic mouse model with DR (two months) compared to control groups." (PMID 35308095, 2022).
lymph node metastasis (3 papers, 2021 to 2022). "In this study, we found that HNRNPA2B1 expression was correlated with patient survival, clinical stage, T classification, and lymph node metastasis." (PMID 34631545, 2021). "Moreover, the mRNA expression of HNRNPA2B1 was examined in eight patients’ fresh cervical lymph nodes samples (four lymph node metastasis and four non-lymph node metastasis) by real-time PCR." (PMID 34631545, 2021). "The results showed that HNRNPA2B1 mRNA levels in lymph node metastasis patients were generally much higher than those in non-lymph node metastasis patients (the mean CT values of tumor samples with or without lymph node metastasis were 15.2572 and 16.5325, respectively." (PMID 34631545, 2021).
lymphoma (3 papers, 2016 to 2024). A malignant (clonal) proliferation of B- lymphocytes or T- lymphocytes which involves the lymph nodes, bone marrow and/or extranodal sites. "In adult T-cell leukemia or lymphoma, splice site mutations in HNRNPA2B1 lead to intron retention and premature truncation." (PMID 39268079, 2024). "According to previous studies, HNRNPA2B1, as an important mRNA processing regulator, plays an important role in lymphoma, tumors, inflammation, and other disease conditions." (PMID 36171892, 2022).
motor neuron disease (3 papers, 2014 to 2021). "MATR3-related pathology, encompassing myopathy and motor neuron disease, represents an illustrative example of multisystem proteinopathy (MSP), such as other diseases associated to mutations in VCP, HNRNPA2B1, HNRNPA1, and SQSTM1 genes." (PMID 34659085, 2021). "SG component proteins with a causal role for motor neuron diseases include TDP-43 (gene symbol TARDBP), FUS, ATXN2, SMN, Tau (gene symbol MAPT), HNRNPA2B1, and HNRNPA1." (PMID 24659297, 2014). "Finally, FUS pull down led to the identification of several interactors with known roles in motor neuron disease or other neurodegenerative disorders, including hnRNPA1, hnRNPA2B1, Matrin3 and FMRP." (PMID 27164932, 2016).
Sepsis (3 papers, 2020 to 2025). Sepsis is defined as life-threatening organ dysfunction caused by a dysregulated host response to infection. "Collectively, these results indicate that the protective effect of BA against sepsis is, at least partially, mediated through its targeting of hnRNPA2B1." (PMID 39887250, 2025). "Here, we found that hnRNPA2B1 positively regulated NLRP3 inflammasome activation in macrophages, suggesting that targeting its activity could offer potential therapeutic strategies for sepsis." (PMID 39887250, 2025).
esophageal squamous cell carcinoma (2 papers, 2021 to 2022). Esophageal squamous cell carcinoma (ESCC) is a type of esophageal carcinoma (EC) that can affect any part of the esophagus, but is usually located in the upper or middle third. "METTL3, WTAP, IGF2BP3, YTHDF1, HNRNPA2B1 and HNRNPC were markedly increased in esophageal squamous cell carcinoma (ESCC) and positively related to the expression of PD-1, whose copy number dynamically affects the enrichment of tumor-infiltrating immune cells." (PMID 36225914, 2022).
Hyperglycemia (2 papers, 2022). An increased concentration of glucose in the blood. "TTR can interact with hnRNPA2B1 to form a TTR-hnRNPA2B1 complex, which plays a critical role in TTR’s anti-angiogenesis function in hyperglycemia via the STAT4/miR-223e3p/FBXW7 signaling pathway." (PMID 36277184, 2022).
infertile (2 papers, 2023 to 2025). "This suggests that reduced expression of HNRNPA2B1 and HNRNPC in stromal cells—key components of endometrial tissue—may serve as diagnostic markers for EMS-related infertility." (PMID 39739380, 2025). "The expression levels of HNRNPA2B1 and HNRNPC in various cell types within the eutopic endometrium of normal fertile women and infertile patients with EMS were analyzed." (PMID 39739380, 2025). "The results showed that HNRNPA2B1 and HNRNPC expression levels were significantly higher in endometrial immune cells from infertile EMS patients but lower in stromal cells." (PMID 39739380, 2025). "The results indicated that the expression levels of HNRNPA2B1 and HNRNPC in endometrial tissue from normal fertile women were significantly higher than those in ovarian tissue from infertile women with EMS." (PMID 39739380, 2025). "In summary, this study proposes HNRNPA2B1 and HNRNPC as potential biomarkers for EMS-related infertility." (PMID 39739380, 2025). "Finally, clinical samples of eutopic endometrium from normal fertile women and infertile ovarian patients with EMS were collected, and immunohistochemical staining was used to analyze the expression levels of HNRNPA2B1 and HNRNPC." (PMID 39739380, 2025). "In summary, the findings suggest that HNRNPA2B1 and HNRNPC could serve as potential biomarkers for EMS-related infertility." (PMID 39739380, 2025). "In summary, this study predicted that HNRNPA2B1 and HNRNPC could serve as potential biomarkers of EMS-related infertility." (PMID 39739380, 2025). "Additionally, HNRNPA2B1 and HNRNPC have potential as biomarkers for diagnosing or monitoring EMS-related infertility." (PMID 39739380, 2025).
metastatic disease (2 papers, 2022). "LncRNA miR503HG comes into contact mostly with heterogeneous nuclear ribonucleoprotein A2/B1 (hnRNPA2B1) and represses metastatic tumor repression by controlling the ubiquitination status of hnRNPA2B1." (PMID 36004931, 2022). "The expression patterns of MIR100HG, hnRNPA2B1 and TCF7L2 in CRC specimens from patients who progressed on cetuximab and patients with metastatic disease were analyzed by RNAscope and immunohistochemical staining." (PMID 35279145, 2022).
neuroblastoma (2 papers, 2022 to 2025). Neuroblastoma (NB) is the most common solid, extracranial childhood tumor. "Studies have shown that hnRNPR and hnRNPA2B1 bind to and stabilize ASCL1 mRNA in a m6A-dependent manner, thereby promoting the progression of neuroblastoma." (PMID 40344709, 2025).
psoriasis (2 papers, 2021 to 2024). An autoimmune condition characterized by red, well-delineated plaques with silvery scales that are usually on the extensor surfaces and scalp. "Meanwhile, compared to healthy controls, the mRNA level of IGF2BP3 in psoriasis lesions was upregulated, and the level of HNRNPA2B1 was significantly downregulated." (PMID 38436011, 2024). "Our results showed that compared with the normal control group, HNRNPA2B1 was significantly down regulated in the three syndrome groups of psoriasis." (PMID 35126107, 2021).
rectal cancer (2 papers, 2021). A primary or metastatic malignant neoplasm that affects the rectum. "HNRNPA2B1 and HNRNPC are mainly related to Astler–Coller B1 rectal carcinoma." (PMID 34778266, 2021).
schizophrenia (2 papers, 2022). A major psychotic disorder characterized by abnormalities in the perception or expression of reality. "In our data, endothelial nuclei derived from schizophrenia exhibited reduced expression of HNRNPA2B1, a gene coding for a heterogeneous ribonucleoprotein involved in the alternative splicing of several genes." (PMID 36192459, 2022).
thymic epithelial tumors (2 papers, 2024). "The ribonucleoprotein hnRNPA2B1 represents a potential target for treating recurrent thymic epithelial tumors." (PMID 38601162, 2024). "By drug repositioning and molecular dynamics simulations, a recent study pointed out that the compound ergotamine may become a reusable drug for treating recurrent thymic epithelial tumors (TET) by targeting hnRNPA2b1." (PMID 39517115, 2024).